RNU4-74P (RNA, U4 small nuclear 74, pseudogene)
Gene: Small nuclear RNA gene on chromosome 7 (141,052,249 to 141,052,409, forward strand). Ensembl gene ENSG00000223212.
Homologues: Orthologues: chimpanzee U4 (93% identical), macaque U4 (84% identical), dog U4 (47% identical), rat LOC120100112 (45% identical). Paralogues in human: RNU4-13P (57% identical), RNU4-44P (55% identical), RNU4-29P (52% identical), RNU4-16P (50% identical), RNU4-73P (49% identical), RNU4-82P (49% identical), RNU4-18P (47% identical), RNU4-48P (47% identical), RNU4-6P (47% identical), RNU4-15P (47% identical), RNU4-57P (47% identical), RNU4-22P (46% identical), and 81 more.